ADAM17 (ADAM metallopeptidase domain 17)
Diseases named in the same sentence as ADAM17 in open-access papers (continued):
Sharing a sentence is not in itself a finding about the gene and the disease.
idiopathic pulmonary fibrosis (14 papers, 2018 to 2025). Idiopathic pulmonary fibrosis (IPF) is a nonneoplastic pulmonary disease that is characterized by the formation of scar tissue within the lungs in the absence of any known cause. "Our study demonstrates that ADAM17 regulates ferroptosis in lung fibroblasts to promote fibrosis development through PTGS2, suggesting a potential therapeutic target in ADAM17 for the treatment of lung fibrosis." (PMID 40077919, 2025). "In other diseases, ADAM17 participated in idiopathic pulmonary fibrosis (IPF) via miR-708-3p/ADAM17/STAT3 signaling pathway." (PMID 34182543, 2021). "Increased ADAM17 expression is identified in several inflammatory diseases, cancers, and organ fibrotic changes including pulmonary fibrosis." (PMID 33260349, 2020). "qRT-PCR and Western blot analysis showed that JAK1, STAT3 and ADAM17 levels increased in the pulmonary fibrosis model in vivo, whereas FFK remarkably decreased JAK1, STAT3 and ADAM17 expression." (PMID 30092799, 2018). "In the current study, the expression level of JAK1, STAT3 and ADAM17 decreased in FFK treatment group compared to BLM treatment group, thus indicating the possible pathways implicated in lung fibrosis as targets of therapeutic attempts." (PMID 30092799, 2018). "In a silica/TGF-induced lung fibrosis model, exosomal miR-26a-5p from human umbilical cord mesenchymal stem cells (HUMSCs) disrupted a disintegrin and metalloproteinase domain-containing protein 17 (ADAM17)/neurogenic locus notch homolog protein (Notch) axis of EMT to lessen scarring in vivo." (PMID 40676634, 2025). "In addition, patients who combined with idiopathic pulmonary fibrosis (IPF) had higher ADAM17 expression than patients with inflammatory myopathies alone, highlighting elevated ADAM17 expression in patients with inflammatory myopathies, particularly IPF." (PMID 40224489, 2025). "However, it is reasonable to infer that ferroptosis itself more likely represents a downstream pathway in ADAM17/PTGS2‐induced lung fibrosis during fibroblast activation." (PMID 40077919, 2025). "Evidence also suggests that the ADAM17–EGFR–ERK pathway contributes to lung fibrosis." (PMID 40224489, 2025). "However, it was shown in vitro that in alveolar epithelial cells, SARS-CoV-2 infection increases the expression of ACE2 and ADAM-17, possibly supporting these as interacting factors in the development of lung fibrosis." (PMID 38892098, 2024). "ADAM17 participates in pulmonary fibrosis by inducing ACE-2 ectodomain shedding." (PMID 33260349, 2020). "However, the intracellular molecular mechanism through which ADAM17 induces lung fibrosis remains unclear, necessitating further studies to elucidate how ADAM17 promotes lung fibrosis development and progression." (PMID 40077919, 2025). "However, the role of ADAM17 in TGF-β-induced EMT in pulmonary fibrosis remain unidentified." (PMID 33260349, 2020). "Therefore, ADAM17 has an important role in lung fibrosis and may be a therapeutic target." (PMID 40224489, 2025). "Mice transfected with the ADAM17‐shRNA virus exhibited a significant reduction in BLM‐induced ferroptosis and lung fibrosis, as evidenced by H&E, Sirius red, Masson trichrome staining and Ashcroft score." (PMID 40077919, 2025). "By targeting ADAM17, miR-708-3p represses the GATA/STAT3 signalling pathway in idiopathic pulmonary fibrosis (IPF) reducing fibrosis." (PMID 38920689, 2024). "ADAM17 is involved in a variety of inflammatory processes, including activation and release of TNF, modulation of neuregulins such as AREG, and being a necessary cofactor for IL6 trans-signaling, which has been shown to promote pulmonary fibrosis in bleomycin injury." (PMID 36291184, 2022).
liver cancer (12 papers, 2015 to 2025). An epithelial or non-epithelial malignant neoplasm that arises from the liver. "It was closely associated with degree of differentiation in liver cancer suggesting that the ADAM17 was associated with the development of liver cancer." (PMID 25351873, 2015). "IL‐1β from liver cancer cells activates EGFR signaling in Kupffer cells via ADAM17 (also known as TACE), leading to IL‐6 production through JNK, p38, and IKK signaling." (PMID 40859900, 2025). "Our study corroborates these findings, as we identified abnormal overexpression of ADAM9, ADAM10, ADAM15, and ADAM17 in liver cancer tissues through both GEPIA website analysis and PCR experiments." (PMID 39346916, 2024). "Prior research has documented a noteworthy upregulation of ADAM family members, particularly ADAM9, ADAM10, and ADAM17, in liver cancer, indicating a close link with tumor advancement." (PMID 39346916, 2024). "The results confirmed that ADAM9, ADAM10, ADAM15, and ADAM17 exhibited an upregulation trend in at least one liver cancer cell line, consistent with our earlier predictions." (PMID 39346916, 2024). "ADAM17 is thought to cleave the Notch receptor and inactivate Notch signaling, thereby impeding the GPR50/ADAM17/Notch axis-mediated development of liver cancer." (PMID 36466812, 2022). "The role of Notch signaling in the development of liver cancers has been recently reviewed however, the direct implication of adamalysins in this pathway remains poorly documented, except for ADAM17." (PMID 33805340, 2021). "ADAM17 was also involved in transactivation of Notch signaling in liver cancer stem cells, contributing to an aggressive phenotype." (PMID 33805340, 2021). "In addition to the ADAM10 gene, ADAM9 and ADAM17 are the other frequently reported genes in liver cancer, playing a crucial regulatory role in chemotherapy resistance and malignant tumor progression." (PMID 39346916, 2024). "We have reported that both AREG and ADAM17/TACE are expressed correspondingly with aromatase in liver tissues and liver cancer cell lines." (PMID 33925807, 2021). "Immunohistochemistry analysis showed a positive correlation between ADAM17 and MMP21 in patients with liver cancer." (PMID 33100908, 2020). "In a liver cancer pathway gene expression profile analysis of HepG2 cells transfected with C/EBPα-saRNA, EGF, EGFR, ADAM17 and β-catenin involved in EMT were down-regulated." (PMID 27050434, 2016).
liver fibrosis (11 papers, 2010 to 2025). "Inhibits EMT and liver fibrosis by targeting Cyclin G1 and ADAM17 and maintains the epithelial phenotype." (PMID 40895189, 2025). "Hepatic fibrosis, which is important risk factor in the prognosis of NAFLD patients is related not only to traditional TGF-β pathway, but also FOSL2, ADAM17, and angiotensin pathway." (PMID 36405611, 2022). "In a recent study, ADAM17 was found to be overexpressed in liver fibrosis in a preclinical study of non-alcoholic steatohepatitis (NASH)." (PMID 35625561, 2022). "The broad role of ADAM17 inhibition on liver injury can also be seen in studies linking ADAM17 activity and hepatic stellate cell signaling in the setting of liver fibrosis in NASH and ADAM17 in overall NAFLD development." (PMID 35095853, 2021). "In this work, we aimed to examine the combined role of ADAM10 and ADAM17 in liver regeneration and liver fibrosis development, using mouse models deficient in ADAM10, ADAM17 or simultaneously deficient for both proteases." (PMID 34075077, 2021). "The impact of ADAM17 inhibition on liver fibrosis development in response to BDL surgery was assessed via Sirius red staining of liver sections to detect collagen deposition." (PMID 35095853, 2021). "Therefore, murine models employing hepatoxic agents such as dimethylnitrosamine, diethylnitrosamine, and carbon tetrachloride over a longer duration of time may be more appropriate to study the role of ADAM17 in liver fibrosis and cirrhosis development." (PMID 35095853, 2021). "Macrophage MerTK activation is enhanced in nonalcoholic steatohepatitis (NASH) due to suppression of its cleavage by ADAM17, which activates hepatic stellate cells (HSC) via the ERK-TGFβ1 pathway to promote liver fibrosis." (PMID 37422464, 2023). "In nonalcoholic steatohepatitis, limiting ADAM17 activity increases MerTK expression in macrophages, which further induces TGF-β1 production, leading to the activation of hepatic stellate cells by TGF-β1 to encourage liver fibrosis." (PMID 40224489, 2025). "Therefore, ADAM17 deficiency is not protective in fibrosis development per se, but can ameliorate the damaging effect of ADAM10 deficiency on liver fibrosis development." (PMID 34075077, 2021). "Interestingly, ADAM17 inhibition did not attenuate liver fibrosis development in BDL mice, possibly reflected by the relatively modest fibrotic response in day 10 BDL mice." (PMID 35095853, 2021). "Thus, ADAM17 elimination was not protective in CCl4 induced liver fibrosis when functional ADAM10 was present, but alleviated aggravating impact of ADAM10 deficiency on fibrosis development." (PMID 34075077, 2021). "However, ADAM17 inhibition in BDL mice by DPC 333 treatment did not alter the development of hepatic fibrosis." (PMID 35095853, 2021).
myocardial infarction (11 papers, 2018 to 2025). Gross necrosis of the myocardium, as a result of interruption of the blood supply to the area, as in coronary thrombosis. "This suggests that inhibiting ADAM17 during myocardial infarction can enhance the clearance of dead cells by macrophages and improve cardiac function." (PMID 41590849, 2025). "Knockout of Adam17 specifically in cardiomyocytes has been shown to ameliorate left ventricular remodeling in diabetic cardiomyopathy and myocardial infarction in mice." (PMID 39014511, 2024). "Cardiomyocyte-specific ADAM17 knockdown mice promotes myocardial infarction recovery by accelerating angiogenesis." (PMID 37046278, 2023). "The expression of ADAM17 was also downregulated in the myocardial infarction area, according to immunofluorescence detection." (PMID 37046278, 2023). "In the cardiovascular system, a short-term increase in ADAM17 expression after acute myocardial infarction can aggravate cardiac dysfunction." (PMID 34035876, 2021). "Notably, the expression of ADAM17, an exfoliating protease, is upregulated during myocardial infarction, resulting in the solubilization of MerTK and its transformation into a soluble Mer." (PMID 41590849, 2025). "Hydrogen peroxide was used to cause cell death in H9C2 cardiomyocytes in order to study the function and mechanism of ADAM17 in damaged myocardium, which has been utilized to simulate myocardial injury in myocardial infarction as it leads to apoptosis and necrosis of cardiomyocytes." (PMID 37046278, 2023). "MiR-26a-5p could target and regulate ADAM17 and reduce the apoptosis of myocardial cells and the expression of inflammatory factors in acute myocardial infarction." (PMID 34912217, 2021). "Moreover, the increased expression of ADAM17, as well as of TNF-α was associated with rupture of atherosclerotic coronary plaques in patients with myocardial infarction." (PMID 33117379, 2020). "Increased ADAM17 activity was observed after myocardial infarction (MI), whereas ADAM17 inhibition decreased the amount of fibrosis after MI in mice." (PMID 36733457, 2023).
asthma (10 papers, 2009 to 2025). "The ADAM17 is involved in TNF-α production, and the association between ADAM17 and asthma has recently been demonstrated through animal experiments." (PMID 35130903, 2022). "The rs12151757 in CPSF3 showed the highest statistical association (P = 9.46 × 10–6) with asthma and this SNP acts as an eQTL of ADAM17." (PMID 35130903, 2022). "The 13 and 8 SNPs in ADAM17 were significantly associated with asthma and allergies, respectively." (PMID 35130903, 2022). "Collectively, CD36 is a critical mediator through which ADAM17 regulates the phagocytic function of AMs in the OVA-induced asthma model." (PMID 41181101, 2025). "We identified HMOX1, ITGAM, SFTPD and ADAM17 as the top novel targets for asthma which need to be validated experimentally whereas IL-18, TNF and VEGFA as the strongest therapeutic targets to investigate further for clinical benefit." (PMID 37735578, 2023). "HMOX1, ITGAM, DDX58, SFTPD and ADAM17 were the top novel targets identified for asthma which needs to be validated experimentally." (PMID 37735578, 2023). "The SNPs in ADAM17 were used in logistic regression analysis to analyze the correlation between asthma and allergies in patient groups and control groups." (PMID 35130903, 2022). "ADAM17 is ubiquitously expressed in human lung tissue, and its expression is up-regulated in lung diseases including asthma, COPD and endotoxin-induced acute lung injury." (PMID 31438559, 2019). "IL-6R, a prominent ADAM17 substrate linking the axis to STAT3 in trans-signaling, is a modifier of COPD as well as asthma." (PMID 29540993, 2018). "Our findings showed that ADAM17, a key downstream effector molecule of TNF-α, impaired AMs phagocytic function by downregulating the expression of the phagocytic receptor CD36, thereby contributing to the pathogenesis of OVA-induced asthma model." (PMID 41181101, 2025). "These include ACE2 and TMPRSS2 in asthma patients as well as ACE2 and ADAM17 in COPD patients." (PMID 34081722, 2021). "One possible explanation for this discrepancy might be related to chronic type 2 airway inflammation induced by interleukin (IL)-13 in the airway epithelium, which could elevate ADAM17 expression, leading to the downregulation of ACE2 expression before COVID-19 infection in patients with asthma." (PMID 38241229, 2024).
Autoimmunity (10 papers, 2013 to 2025). The occurrence of an immune reaction against the organism's own cells or tissues. "In primary Sjögren’s disease (pSjD), an autoimmune disorder characterized by chronic inflammation, the role of ADAM17 has been extensively explored, but a correlation with Notch2 has not yet been evaluated." (PMID 41517433, 2025). "In conclusion, in this review, we provide an overview of the most recent advances in the knowledge on the diverse molecular mechanisms involving ADAM17 activation in autoimmunity." (PMID 39768182, 2024). "In this review, we summarize the most recent updates on the multiple regulatory activities of ADAM17, focusing on reported data in the field of autoimmunity." (PMID 39768182, 2024). "Shedding by ADAM10 and ADAM17 is a highly regulated mechanism in multiple conditions including inflammation, cancer, and autoimmunity." (PMID 38897568, 2024). "This broad role played by ADAM17 in the initiation and propagation of inflammation has made the development of ADAM17 inhibitors an appealing target for treating numerous chronic inflammatory and autoimmune conditions." (PMID 35095853, 2021). "However, it is well conceivable that under different circumstances, such as responses to other pathogens or to tumors or in autoimmunity, T cells might require ADAM17 for proper function." (PMID 28877252, 2017). "Alternatively, excess ectodomain shedding of MerTK and CD163 by ADAM-17 may account for a functional impairment of M2c monocytes/macrophages and could itself contribute to chronic inflammation, defective clearance of early ACs and autoimmunity." (PMID 24325951, 2013). "Upon validation, the targeting of ADAM17 may be exploited to prevent tumor metastasis, while the enhanced apoptotic response of T-cells lacking ADAM17 could be facilitated to reduce the quantity of aberrant T-cells in leukemia, autoimmunity and inflammatory diseases." (PMID 34831323, 2021).
cervical carcinoma (10 papers, 2013 to 2024). A carcinoma arising from either the exocervical squamous epithelium or the endocervical glandular epithelium. "Others reported that the expression of ADAM17 is associated with aggressive progression and poor prognosis in cervical cancer." (PMID 39286024, 2024). "We detected expression of ADAM17 in all cervical cancer cell lines, and abundance of the pro-form (P) of ADAM17 was comparable between lines and culture conditions, while the active form (A) was expressed more prominently in the spheroid conditions." (PMID 39286024, 2024). "ADAM17-modified bone marrow mesenchymal stem cells may stimulate the malignant growth of drug-resistant cervical cancer cells by activating the EGFR/PI3K/Akt pathway." (PMID 36466812, 2022). "Here, we present a comparison of multiple cellular model systems to study novel combinatorial treatments to overcome chemotherapy resistance in cervical cancers focusing on the inhibition of the metalloproteases ADAM10 and ADAM17." (PMID 39286024, 2024). "BING ZHAO and MENGCAI HU demonstrated in their study on cervical cancer cells that gallic acid exhibits inhibitory effects on the expression of ADAM17, EGFR, p-AKT, and p-ERK, thereby effectively impeding the progression of cervical cancer." (PMID 39045282, 2024). "Indeed, the protein levels of a disintegrin and metalloproteinase 17 (ADAM17), amphiregulin (AREG), ECM metalloproteinase inducer (EMMPRIN), and MMP were increased in cervical carcinoma clinical samples when compared with normal adjacent cervical tissues." (PMID 30208169, 2018). "ADAM17 is an important member of the ADAM family involved in the proteolysis of collagen IV of the ECM and also the release of several integrins from the cell surface, indicating that ADAM17 affects the migration activity of a variety of cells, including cervical cancer cells." (PMID 24843386, 2013).